RN7SKP140 (RN7SK pseudogene 140)
Gene: Miscellaneous RNA gene on chromosome 20 (21,424,758 to 21,425,041, reverse strand). Ensembl gene ENSG00000223128.
Homologues: Orthologues: chimpanzee 7SK (98% identical). Paralogues in human: RN7SKP9 (75% identical), RN7SKP8 (75% identical), RN7SKP255 (74% identical), RN7SKP77 (74% identical), RN7SKP146 (74% identical), 7SK (74% identical), RN7SKP127 (74% identical), RN7SKP180 (74% identical), RN7SKP20 (74% identical), RN7SKP294 (74% identical), RN7SKP124 (73% identical), RN7SKP184 (73% identical), and 284 more.